LEP (leptin)
Diseases named in the same sentence as LEP in open-access papers (continued):
Sharing a sentence is not in itself a finding about the gene and the disease.
Hyperglycemia (continued). "We show for the first time that hyperglycemia alone directly enhances leptin signaling in both non-tumorigenic and malignant breast epithelial cells." (PMID 24260287, 2013). "Here, we demonstrate that hyperglycemia clearly increases proliferation of both non-tumorigenic and malignant mammary epithelial cells and this is accomplished by increased leptin signaling and pro-survival AKT/mTOR signaling." (PMID 24260287, 2013). "Mice lacking the receptor for the satiety regulator leptin are hyperphagic and demonstrate increased post-natal weight gain, which promotes hyperinsulinaemia and eventually hyperglycaemia." (PMID 23971965, 2013). "Prior to the injection, the ob/ob mice were obese (average initial body weight 53 g and 51 g in the leptin treatment and control groups, respectively), without prominent hyperglycemia." (PMID 24009765, 2013). "Lipid peroxidation is also increased in brain of streptozotocin-induced diabetic rats, suggesting that lipid peroxidation is not solely related to defective leptin signaling and hyperglycemia." (PMID 24163719, 2013). "Hyperglycemia in mothers with GDM is a teratogenic condition that affects organogenesis and induce epigenetic changes primarily through insulin production, modifications Melanocortin 4 receptor, lipoprotein lipase, and leptin methylation patterns, and increased adiposity in the growing fetus." (PMID 40319278, 2025). "Therefore, the disorder of steroidogenesis and spermatogenesis in db/db mice is more likely due to hyperglycemia and other metabolic problems but not the lack of leptin." (PMID 38817616, 2024). "The lack of difference in relation to hyperglycemia for milk leptin, adiponectin, leptin–adiponectin ratio, resistin, and IGF-I levels might be the outcome of effective treatment of GDM during pregnancy." (PMID 38612666, 2024). "However, emulsifier-treated females exhibited fasting hyperglycemia and presented mild glucose intolerance with no changes in plasma leptin levels." (PMID 37616199, 2023). "However, this concept is not entirely valid as, despite the high leptin levels following ovariectomy, it did not correct the hyperglycemia or protect against the deterioration in lipid profile." (PMID 35486321, 2022). "Further, AgRP neuron function is not required for T1D hyperglycemia or leptin’s rescuing effects." (PMID 33976218, 2021). "However, as Arc GABAergic LepRArc neurons are the primary mediator of the leptin action in T1D, POMC neurons, which are non-GABAergic21, may contribute little to T1D hyperglycemia and leptin action in reducing T1D glucose." (PMID 33976218, 2021). "However, the conditional deletion of Grin2b from AgRP neurons in ob/ob mice leads to a complete prevention of hyperglycemia-induced by the lack of leptin signaling, independently of changes in body weight and food intake." (PMID 32823489, 2020). "To test our hypothesis, we generated insulin-deficient mice lacking LEPRs in RIP-Cre25Mgn neurons (RIP-CreΔLEPR) and examined whether i.c.v. leptin injection can lower hyperglycemia in these mice without insulin." (PMID 33071988, 2020). "This leptin administration also did not affect abdominal fat accumulation in the male and female offspring regardless of diet and abolished the presence of hyperglycaemia in obese animals." (PMID 31703240, 2020). "Leptin infusion or gene therapy, can reverse hyperglycemia without a detectable rise in circulating insulin levels in STZ-treated rats and mice, non-obese diabetic (NOD) mice, insulin deficient Akita mice and BioBreeding rats with virally-induced beta cell destruction." (PMID 31231496, 2019). "Furthermore, LepRbHtr2cKO mice exhibited neither hyperglycemia nor alteration in serum insulin or leptin concentrations." (PMID 29914853, 2018). "The lacks of our study are that we have not measured leptin and insulin levels, but hyperglycemia was observed in the EV-induced PCOS animal model, which it may be due to the increase in sympathetic activity." (PMID 26577050, 2015).
Hyperglycemia (continued). "In contrast to leptin, adiponectin and resistin were not altered 2 h after glucose uptake and this is in agreement with recent studies indicating that systemic adiponectin and resistin are not influenced upon acute hyperglycemia and/or hyperinsulinemia." (PMID 17311679, 2007). "Treatment of diabetic rats with INI moderately reduced hyperglycemia without causing hypoglycemic episodes, attenuated hyperphagia, and in the case of T2DM and diet-induced MS, INI increased tissue sensitivity to insulin and leptin and normalized glucose tolerance." (PMID 36834685, 2023). "Additionally, much of the literature has focused on the long-term effects of FGF1 using diabetic rodent models with disrupted leptin signaling, and much less is known about the mechanisms underlying acute effects of FGF1, which are independent of long-term reductions in hyperglycemia." (PMID 34987476, 2021). "Thus, leptin may sensitize neurons in the hypothalamus to the effects of insulin but may also exert central effects independent of insulin, as is supported by the fact that leptin can reverse hyperglycemia in mice with streptozotocin-induced type 1 diabetes." (PMID 31133864, 2019). "Metformin significantly reduced hyperglycemia, but did not affect adiponectin or leptin levels in obese mice, and so this study did not address whether an anti-diabetic medication that could alter these adipokine levels might have efficacy in the treatment of obese asthma." (PMID 26610598, 2015). "Previous data have shown that maternal obesity and hyperglycemia affect offspring neurodevelopment; hypothalamic neurocircuits from the ARC to the PVH are underdeveloped in offspring of obese or gestational diabetic dams and this may be due to a prolonged postnatal leptin surge." (PMID 24684305, 2014). "A difference was found for milk ghrelin, but not for molecules such as adiponectin, leptin, resistin, or IGF-I levels, in relation to maternal hyperglycemia." (PMID 38612666, 2024). "A similar result was found in another experiment that involved IRS1 knockout mice lacking hepatic IRS2, it was observed that leptin, IGF1 levels was decreased, glucose tolerance ability was impaired and resulted in hyperglycemia." (PMID 35241081, 2022). "We found that prenatal exposure to leptin during mid‐pregnancy did not prevent DIO development, but it did abolish hyperglycaemia in obese animals of both sexes." (PMID 31703240, 2020). "In the status of absent of leptin, APF could not normalize the hyperglycemia and hyperinsulinemia of ob/ob mice." (PMID 36046814, 2022). "The lack of difference in the pattern of leptin, adiponectin, LAR, resistin, and IGF-I levels between GDM and non-GDM mothers observed in our study might be the outcome of the implementation of quick and effective treatment of hyperglycemia during pregnancy." (PMID 38612666, 2024).
Hyperinsulinemia (372 papers, 2007 to 2026). An increased concentration of insulin in the blood. "Patients with LEP variants can present with hyperinsulinemia and history of infections, especially upper respiratory tract infections, potentially resulting from abnormal T‐cell counts and function." (PMID 40528426, 2025). "Leptin production in obese tissue is caused by chronic inflammation, hyperinsulinemia and significant lipid disturbances in CKD patients." (PMID 36871015, 2023). "Hyperinsulinemia in the offspring of various animals has been linked to transference of breast milk hormones such as insulin and leptin." (PMID 37899888, 2023). "It has been shown that chronic insulin exposure can induce leptin secretion and production and hyperinsulinemia causes leptin resistance in hippocampal neurons." (PMID 38068822, 2023). "Studies have shown that blocking the cannabinoid 1 (CB1) receptor leads to fat loss, reverses the overproduction of leptin and insulin, and has a protective effect on hyperinsulinemia and beta cell dysfunction." (PMID 36600288, 2023). "Animal studies from our laboratory have also shown that maternal obesity is associated with glucose intolerance, hyperinsulinemia, increased leptin level, and hyperphagia in male rat offspring." (PMID 35163366, 2022). "Homozygous LEP autosomal recessive mutations are correlated to the expression of disease phenotypes including hyperphagia, hyperinsulinemia, immune system dysfunction, and infertility." (PMID 34504472, 2021). "For example, maternal obesity and early childhood obesity cause hyperinsulinemia and hyperleptinemia combined with insulin- and leptin-insensitivity." (PMID 34211985, 2021). "To exclude possible HFD-specific effects of MLN4924, we examined the leptin-deficient ob/ob mice, whose uncontrolled food intake elicits hyperinsulinemia and low ETV5 levels under normal diet." (PMID 33911083, 2021). "Leptin production is regulated through overfeeding, hyperinsulinemia, glucocorticoids, and TNFα, while the decrease in leptin is associated by amongst others fasting, cAMP, testosterone and the growth hormone (GH)." (PMID 31849810, 2019). "The increased results of the insulin and leptin suggest that the leptin resistant occurred in increased leptin and it caused hyperinsulinemia." (PMID 30622594, 2018). "Concurrent reductions in hyperinsulinemia, leptin, LDL-cholesterol, and RAS were associated with the sympathoinhibition attained." (PMID 27857694, 2016). "In these models, the relative contribution of IR-associated hyperinsulinemia and central leptin resistance is difficult to disentangle, particularly since hypothalamic insulin signaling also regulates GnRH release and thus reproduction function." (PMID 27375552, 2016). "It has been shown that the introduction of MSG causes lesions in the arches and ventromedial nuclei of the hypothalamus, causing insensitivity to leptin and insulin in this region resulting in developing hyperleptinemia and hyperinsulinemia." (PMID 24410812, 2014). "Weight loss, fasting, and starvation reduce leptin concentrations, while weight gain and hyperinsulinemia have the opposite effects." (PMID 23691290, 2013). "Conversely, trans-10, cis-12 CLA-caused hyperinsulinemia associated with lipid steatosis in Ob/Ob mouse which lack functional leptin suggests the involvement of other factors." (PMID 21869929, 2012). "Since leptin is associated with hyperinsulinemia and glucose intolerance and has atherogenic effects, it is speculated that abnormal blood glucose in the intracranial arteries is also associated with lumen wall thickening." (PMID 40520614, 2025). "Even though the precise relationship between Cdc42, insulin, and leptin in blood vessels is unknown, it is reasonable to assume that Cdc42 activation is linked to vascular remodeling caused by age-related hyperinsulinemia and hyperleptinemia." (PMID 38068822, 2023).
Hyperinsulinemia (continued). "It has been verified that plasma leptin may be a reliable predictor of PCOS, and high leptin levels are strongly associated with both hyperandrogenism and hyperinsulinemia." (PMID 37929034, 2023). "Therefore, hyperleptinemia and leptin in group I can be associated with hyperinsulinemia and IR, as evidenced by the established correlations between leptin and HOMA-IR (ρ=0.65), the ratio of L/BMI and Caro index (ρ=0, 8) (p<0.05)." (PMID 35126755, 2021). "All nine carriers were leptin deficient, and three subjects exhibited hyperinsulinemia." (PMID 34504472, 2021). "Rodents treated at neonatal age with monosodium l-glutamate (MSG), which destroys 80%–90% of the ARC neurons, develop neuroendocrine and metabolic abnormalities, resulting in a phenotype of adiposity characterized by GH deficiency, hyperinsulinemia, and hyperleptinemia due to leptin resistance." (PMID 26371051, 2015). "An elevated plasma leptin in the HFAR rats could be linked to the observed hyperinsulinemia in this group of rats." (PMID 24294136, 2013). "This leptin resistance might be the result of dysfunction of adipocytes or pancreatic cells and could be the cause of further hyperinsulinemia and a progressive positive loop mechanism." (PMID 23227034, 2012). "In addition, hyperinsulinemia was combined with a loss of protective leptin signaling due to a decrease in adipocyte surface area and a consequent decrease in their ability to excrete leptin and adiponectin." (PMID 37929025, 2023). "Elevated leptin levels result in declined responsiveness of pancreatic β cells, inability to suppress insulin secretion, and hyperinsulinemia." (PMID 41549047, 2026). "The majority of obese individuals manifest a state of chronic hyperinsulinemia leading to defective leptin signaling, resulting in “brain starvation”, which prevents the negative feedback that would normally suppress food intake." (PMID 40950761, 2025). "Insulin and Leptin Resistance: Diets rich in refined carbs and added sugars can lead to hyperinsulinemia and leptin dysregulation, perpetuating cravings and overeating." (PMID 41573037, 2025). "Persistent hyperinsulinemia has been shown to elevate leptin levels in humans, suggesting that leptin secretion is influenced by glucose metabolic pathways." (PMID 41423640, 2025). "In this study, commensurate with an increase in adipose mass and hyperinsulinemia, serum leptin levels were elevated in paternally BPA‐exposed offspring." (PMID 39792613, 2025). "Sustained hyperinsulinemia and elevated leptin levels, observed in the high-H group of relatives, have been associated with increased apoptosis of β-cells and a reduction in β-cell mass." (PMID 39656436, 2025). "No change in GWG, improved lipid profile, reduction in circulating leptin and adiponectin, correction of fasting hyperinsulinemia (Sema-treated dams only) before and during pregnancy." (PMID 41359794, 2025). "Renal function has been observed to only partially influence leptin levels in CKD patients, the main determinant being leptin overproduction in adipose tissue due to hyperinsulinemia and chronic inflammation." (PMID 39062887, 2024). "These complications are thought to be mediated by complex and not fully understood mechanisms, encompassing IR and promoting hyperinsulinemia, elevated leptin levels, chronic low-grade systemic inflammation, and oxidative stress (OS)." (PMID 38892561, 2024). "Further, higher body fat content enhances the sympathetic tone, activation of the renin-angiotensin system, hyperinsulinemia, and secretion of adipokines such as leptin and all these derangements can potentially lead to high BP." (PMID 37848999, 2023). "The second factor is high levels of leptin and hyperinsulinemia, which have been shown to induce carcinogenesis." (PMID 36800961, 2023). "The age-related increase in fat mass and hyperinsulinemia triggers an imbalance of leptin-dependent regulation of adipose tissue homeostasis." (PMID 38068822, 2023).
Hyperinsulinemia (continued). "Overall, the associations found in this study are in concordance with previous reports, pointing towards a link between weight gain, elevation of leptin levels, hyperinsulinemia and consequently increased adrenal androgen production." (PMID 37009276, 2023). "In rodents and humans, LEP and LEPR deficiencies are associated with hyperinsulinemia, hypothyroidism, and hypogonadotropic hypogonadism resulting in delay or absence of pubertal development." (PMID 37659411, 2023). "Hyperinsulinemia, though significantly more pronounced in individuals with LEPR or MC4R deficiency compared with those with LEP deficiency, increased with age in all three mutant groups." (PMID 37659411, 2023). "Reduced leptin signaling in pancreatic beta cells due to leptin resistance leads to increased secretion of insulin (hyperinsulinemia)." (PMID 36381191, 2022). "Prepubertal fast growth seems to be dependent on the increased bioavailability of IGF-1 as a result of hyperinsulinemia and on the skeletal growth-promoting effect of increased leptin levels on chondrocyte proliferation and maturation." (PMID 36263328, 2022). "Hyperinsulinemia promotes the secretion of leptin by adipocytes, and leptin levels are significantly elevated in MetS patients." (PMID 35813613, 2022). "A high dose of MG741 treatment not only reduced the body weight gain and fat deposition induced by an HFD but also improved fasting hyperinsulinemia and decreased serum leptin levels." (PMID 35565930, 2022). "Secondly, high leptin levels can lead to hyperinsulinemia, which makes the liver produce cholesterol-supersaturated bile." (PMID 35346065, 2022). "Some experimental studies have also suggested that hyperphagia, hyperinsulinemia, and higher levels of serum leptin and body weight following a decrease in BDNF levels, among BDNF-knockout mice." (PMID 34580389, 2021). "The supplementation with T. lutea partially prevented hyperinsulinemia observed in the HF group and restored the basal leptin level, whereas it was observed the lowest glycemia in the HF-Tiso group (ANOVA, p < 0.001)." (PMID 33525643, 2021). "Intravenous injection of leptin-neutralizing antibodies was reported to induce hyperinsulinemia in mice." (PMID 33953692, 2021). "The administration of leptin also reverted the hyperinsulinemia, corticosterone levels, and infertility problems related to the mutated mice." (PMID 34504472, 2021). "It is very likely that the increased leptin levels in the blood of CKD patients result from leptin overproduction in the adipose tissue due to hyperinsulinemia and chronic inflammation (increased levels of CRP, IL-6, IL-10, and TNF-α)." (PMID 33925217, 2021). "Tunicamycin-administered mice developed hyperinsulinemia, augmented lipolysis and increased circulating leptin and adiponectin." (PMID 33430288, 2021). "In T2DM, overweight patients are not only high serum free fatty acids and hyperinsulinemia, but also increased leptin, MCP-1, IL-6, and TNF-α production by adipocytes." (PMID 34003397, 2021). "We found a higher frequency of metabolic abnormalities in LEP wt/- than in wt/wt subjects, including hypercholesterinemia, hyperinsulinemia, and hypertriglyceridemia in two studies." (PMID 34448070, 2021). "They exhibited significant decreases in plasma adiponectin and increases in leptin, glucose intolerance and hyperinsulinemia." (PMID 30728429, 2019). "Hyperinsulinemia was previously reported to have a long-term stimulatory effect on leptin production." (PMID 31975995, 2019). "This early observed hyperinsulinemia, hyperleptinemia and hypoadiponectinemia indicates that the known development of insulin and leptin resistance in adults born with IUGR manifests early in childhood." (PMID 30356143, 2018). "This reduction in food intake is partially attributable to the anorexic effect of insulin and leptin on the hypothalamus, which is upregulated in dexamethasone-treated rats as they develop hyperinsulinemia and hyperleptinemia." (PMID 30532777, 2018).